IL6 (interleukin 6)
Diseases named in the same sentence as IL6 in open-access papers (continued):
Sharing a sentence is not in itself a finding about the gene and the disease.
cancer (continued). "In contrast, the role of estrogen as an anti-inflammatory agent has also been documented in several cancers, including that of the liver (incidence ratio between men versus women ranges from 2:1 to 4:1), where estrogen inhibits the production of the inflammatory cytokine interleukin 6 (IL-6)." (PMID 35008370, 2021). "Furthermore, elevated IL-6 levels in HCV infected patients are associated with disease progression, probably due to the IL-6 ability to decrease apoptosis of HCC cells, thereby conferring survival advantage for cancer cells." (PMID 32266003, 2020). "Huameng Li et al24 found Bazedoxifene could inhibit IL‐6 signalling in cancer cells." (PMID 32164044, 2020). "Therefore, it is plausible that targeting the IL-6 signalling pathway may be of therapeutic benefit in HPV+ cancers." (PMID 32899142, 2020). "The findings in mice indicate that IL-6 may have a role in mediating anti-cancer effects." (PMID 32393961, 2020). "Therefore, as a therapeutic alternative for cancer, targeting IL-6 is progressively enticing." (PMID 33014057, 2020). "Additionally, the molecular microenvironment changes upon therapy and can affect the therapeutic outcome; increased soluble chemokines and cytokines including interleukin 8 (IL-8) and interleukin 6 (IL-6) have been detected in a variety of cancers and such cytokine surges can promote metastasis." (PMID 32434541, 2020). "Importantly, the epithelial lesions are preceded by enhanced activation of cytoplasmic and nuclear NF-κB promoting significant molecular alterations of cancer-related genes, such as Bcl2, Egfr, Stat3, Tnf, and Il6, and miRNA markers, such as miR-21, miR-155, miR-192, miR-375, miR-451a, and miR-34a." (PMID 32344873, 2020). "We may hypothesize that the lower expression of IL-6 determined in M. U-care–treated mice would be related to a decrease in cancer cell proliferation, in which IL-6 could act on Bcl-2 expression, altering the proliferation/apoptosis balance toward neoplastic cell apoptosis." (PMID 32423132, 2020). "In ovarian cancer, upregulated lncRNA-HOTTIP can stimulate the production and secretion of IL-6 by regulating transcription factor c-jun, and increase the level of PD-L1 in TANs, and in turn refraining the activity of T cells, and ultimately facilitating immune escape of cancer cells." (PMID 33148302, 2020). "That is, IL‐6 is a pleiotropic cytokine known to also contribute to the development of protective antitumor immunity, which may account for its differential effect on patient survival in different cancers." (PMID 32383556, 2020). "For TTS, CRP ≥ 100mg/dL, elevated IL‐6, ≥ 2 organ comorbidities and decreased lymphocyte counts, were selected via univariate analyses as possible relevant prognostic factors: after variable selection, an adjusted HR = 0.87 for cancer patients was observed (95% CI: 0.46‐1.65, P = .67)." (PMID 32931637, 2020). "Therefore, our more in-depth insight into the IL-6 function in the context of ageing, tumourigenesis and infections may bring new therapeutic strategies for the treatment of age-related disorders, cancer and transmissible, e.g., viral, diseases." (PMID 33114676, 2020). "To test this hypothesis, we added neutralizing anti-human IL6 antibodies to the co-cultured conditioned medium and found that although the co-cultured CM dramatically promoted cancer cell migration, invasion, and EMT, the anti-IL6 antibodies significantly abolished these effects." (PMID 32308766, 2020). "It seems possible that cancer-derived circulating IL6 or GDF15 may trigger the activation of BATs." (PMID 33182625, 2020). "In addition, the effectiveness of topical pre-application of BAY 11-7082 in inhibiting the acidic bile-induced transcriptional activation of cancer-related pro-inflammatory Il6 and Ptgs2, as similarly observed by its co-administration on HM, indicates their activation mediated by NF-κB occurs early." (PMID 32934775, 2020).
cancer (continued). "Furthermore, the addition of IL6 or IL1β neutralizing antibodies to the co-culture system between luc-AsPC-1 cells and human SCs significantly impaired cancer cell dissemination in vivo, as shown by a lower incidence of lung metastasis and a decreased bioluminescence signal." (PMID 32308766, 2020). "Interestingly, this score significantly correlated with many cancer hallmarks associated with immune response, including TNF-α signaling via NF-κB, IL2, and STAT5 signaling; IL6, JAK, and STAT3 signaling; inflammatory responses; IFNα response; and IFNγ response." (PMID 32988398, 2020). "Moreover, the combination of IL-6 with existing conventional diagnostic tools such as RMI score and ROMA or conventional biomarkers CA125 and HE4 improved the ability of the tests to identify patients with malignant ovaries." (PMID 32042020, 2020). "Indeed, visceral obesity, considering the adipocytes and infiltrated immune cells, is particularly related to the increase concentration of this cytokines (TNF-α, IL-6, adiponectin, visfatin and so on), evidencing the important link between adipose tissue, inflammation and cancer." (PMID 33371214, 2020). "Thus, it is possible that increased expression of IL-6 by activated fibroblasts may contribute to cancer’s cisplatin resistance." (PMID 32637576, 2020). "Also, species barriers may preclude engraftment of cancer cells that may critically depend on certain microenvironmental signals, among them the species-specific IL-6 signaling." (PMID 33020483, 2020). "The correlation analysis of hnRNPs with cancer‐related pathways suggested that hnRNPs significantly contributed to the activation or suppression of various oncogenic pathways including protein secretion, mitotic spindle, G2/M checkpoint, DNA repair, IL6/JAK/STAT3 signal and coagulation." (PMID 32915499, 2020). "In addition, macrophages/monocytes produce multiple pro-angiogenic factors, such as vascular endothelial factor (VEGF), granulocyte macrophage colony-stimulating factor (GM-CSF), IL-1, and IL-6, all of which are known to have significant effects on cancer cells." (PMID 33396862, 2020). "Therefore, targeting TIM‐4 may offer a potential pharmacological target in IL‐6 overexpressed cancers." (PMID 32020709, 2020). "Thus, it may be a feasible way for P. gingivalis and F. nucleatum to facilitate the development of OSCC, and by decreasing IL-6 and IL-8, the growth and invasion of cancer cells could be inhibited." (PMID 33003438, 2020). "Thus, our results suggest that CAF-derived IL-6 can contribute to protecting cancer cells from chemotherapy and that IL-6 could be a relevant therapeutic target." (PMID 32528731, 2020). "Therefore, M-CSF is speculated to affect the production of IL-6, TNF-α, and TGF-β via the activation of macrophages, and thereby associated with cancer-related inflammation symptoms." (PMID 33050250, 2020). "Combined therapy by targeting TAMs, CD59 and IL-6 may be a direction for cancer treatments." (PMID 31685825, 2019). "However, in cancer cells, cytokine and growth factor receptors become constitutively activated, most commonly by the autocrine or paracrine expression of their respective ligands such as interleukin 6 (IL-6) and epidermal growth factor (EGF)." (PMID 31816985, 2019). "In addition to enhancing cancer cell proliferation and survival, IL-6 induces EMT via JAK-STAT3 or NF-κB pathways, leading to the induction of several EMT-TFs such as Snail, Slug, Twist, and Zeb1, which suppress the expression of CDH1 via the recruitment of epigenetic regulators." (PMID 31557902, 2019). "However, the complicated interplay among IL-6, DNMTs, and cancer stemness-related genes, such as OCT4, still remains unclear." (PMID 31771617, 2019).
cancer (continued). "Interleukin (IL)-6 drives many of the cancer ‘hallmarks’ through downstream activation of the Janus kinase/signal transducer and activator of transcription 3 (JAK/STAT3) signaling pathway, we wanted to find whether STAT3 plays a role in IL-6-induced MMP2 and MMP9 expression." (PMID 31409371, 2019). "Besides, NF‐κB can also induce the gene expression of IL‐6 that supports cancer cells survival." (PMID 31222971, 2019). "Furthermore, chronic IL-6 exposure in cancer patients may induce not only wasting in skeletal muscles due to increased protein breakdown and decreased induction of post-prandial muscle protein synthesis, but also tumorigenesis." (PMID 31010015, 2019). "Notably, these cancer biomarkers functionally comprised of several cytokines (IL-6, MIF, TGF-α, TNFα), apoptosis-related proteins (sFas, sFasL, TRAIL), growth and angiogenic factors (FGF2, HGF, SCF, VEGF), hormones (leptin, prolactin) and other biomarkers (AFP, OPN), but not carcinoma antigens." (PMID 31089160, 2019). "We could use PIM1 inhibitors or antibody against IL-6 to explore the anti-cancer effect." (PMID 30989585, 2019). "Also, studies have shown that IL-6 contributes to cancer’s drug resistance." (PMID 30744595, 2019). "Moreover, transcription factors, EMT inducers, and epigenetic regulators, including miRNAs, some of which may be induced during inflammatory responses, operate within molecular interacting feedback loops to affect IL-6-induced cancer cell progression." (PMID 31557902, 2019). "For instance, IL-34 stimulates intestinal immune cells to make TNF-α and IL-6, two cytokines exerting proliferative effects on CRC cells, and has been involved in the suppressive function of regulatory T cells, a subset of T cells whose activity associates with the progression of cancer cells." (PMID 29423057, 2018). "Moreover, in obese patients, the cytokines produced by adipocytes and immune cells could promote the survival of cancer stem cells (CSCs) through the activation of the Notch3 and IL-6/JAK2/STAT3 pathways, as demonstrated in other cancer models." (PMID 30366466, 2018). "IFN-γ and TNF-α-treatment resulted in the induction of IDO and IL-6 gene expression and release in established cell lines, suggesting that the elicitation of PCa-TDSFs by these cytokines might contribute to progression of cancer into an untreatable phenotype." (PMID 29896191, 2018). "Moreover, IL-8 and IL-6, the two cytokines with the strongest correlations to circulating H3Cit, were the only cytokines prognostic for short-term mortality in our cohort of cancer patients." (PMID 29324871, 2018). "In our study, we demonstrated that the elevation of plasma IL-6 concentration was inhibited in the KF group, suggesting that βHB induction by KF ingestion might have suppressed the systemic inflammatory response and thereby inhibited cancer progression." (PMID 29443873, 2018). "However, IL-6 might be useful as a bed-side test in general practice, possibly identifying patients with unspecific or vague symptoms of cancer." (PMID 30038723, 2018). "IL6 being a pleiotropic cytokine may arise from multiple sources in cancer patients." (PMID 29540470, 2018). "These could be mediated through several cancer-promoting factors such as IL-6 and IL-8." (PMID 29707149, 2018). "Furthermore, IL-6 levels in cancer tissues and serum are elevated in HCC patients." (PMID 30564277, 2018). "Using a panel of PCa cells, including cell lines from AAM, we also elucidated that exogenous IL‐6 upregulated expression of the epigenetic reader methyl CpG binding domain protein 2 (MBD2), specifically the alternative mRNA splicing variant MBD2_v2, to promote cancer stem‐like cells (CSCs)." (PMID 29741809, 2018).
cancer (continued). "Elevated level of IL-6 expression is associated with cancer cell proliferation, angiogenesis, and metastasis via fueling signal transducer and activator of transcription 3 (STAT3), mitogen-activated protein kinase (MAPK), and Akt signaling, thus promoting EMT and subsequent cancer metastasis." (PMID 29357946, 2018). "Also, we observed a common trend showing a significant correlation between median serum IL-6 and increasing cancer stages, which indicate that IL-6 may be a marker for a more severe type of cancer." (PMID 30038723, 2018). "Moreover, IL-6 was shown to maintain chronic inflammation and thus promotes disease progression, for example, autoimmune encephalomyelitis, arthritis, pristine-induced lupus, plasmacytomas, and various cancers including HCC." (PMID 30591653, 2018). "Moreover, building mouse cancer models, or tissue-engineered 3D models, that more accurately model the effects of targeting IL-6 in the human should lead to better clinical results in the future and avoid the pitfalls of wasted time and money on unsuccessful clinical trials." (PMID 30671025, 2018). "Given that IL-6 is not cancer specific, the use of IL-6 as a diagnostic biomarker is challenging." (PMID 30038723, 2018). "Studies have shown that Res may cause IL-6 changes in cells and further downregulate the expression of p-STAT3 and NF-κB; the development of Cis resistance is also associated with the continuously activated p-STAT3 and NF-κB in cancer cells." (PMID 29390972, 2018). "Similarly, a meta-review of 48 clinical studies concluded that inhibition of IL-6 has unknown and unproven effects on decreasing GI (gastric, pancreatic, colorectal, bile duct and gall bladder) cancer syndromes or improving quality of life." (PMID 30671025, 2018). "In vitro, the release of IL-6 may induce expansion of CD133-positive cancer progenitor cells." (PMID 30104473, 2018). "Additionally, no meta-analyses concerning the relationship between IL-6 promoter polymorphisms and cancer prognosis." (PMID 29552316, 2018). "Similarly, anti-IL-6 therapy holds potential to alleviate cancer-related symptoms." (PMID 29946544, 2018). "Thus, IL-6 is one of the cytokines that has an important role in cancer pathogenesis." (PMID 29794990, 2018). "Moreover, the cytokines involved in cancer-related inflammation, IL-6 and TNFα, may induce neutrophilia." (PMID 29890986, 2018). "Indeed, IL-6 requires Notch3 activity to promote cancer cell invasion and self-renewal." (PMID 30154786, 2018). "However, the therapeutic inhibition of IL-6- and leptin-evoked signaling via Stat3 inhibitors or rapamycin in cancer therapy might still be a challenge due to systemic effects." (PMID 30224299, 2018). "Therefore, blocking IL-6 signaling is a potential therapeutic strategy for cancer patients." (PMID 30134951, 2018). "In addition, ADAM-17 has been shown to cleave the interleukin-6 receptor (IL-6R) resulting in the shedding of soluble interleukin-6 (sIL-6) which is a prerequisite for the pathogenesis of interleukin 6 (IL-6) trans-signaling effecting multiple cellular functions related to cancer and inflammation." (PMID 29393911, 2018). "Thus, future studies should evaluate whether TNF-α triggered IL-6 secretion in VSMC is achieved through similar mechanisms described for cancer cells and macrophages." (PMID 29750813, 2018). "Understanding IL-6-mediated signaling may facilitate the design of better cancer therapeutics." (PMID 28725043, 2017). "Cancer-induced pain results from a mixture of mechanisms, including inflammatory, neuropathic, and/or ischemic components, of which, the synthesis and release of proinflammatory cytokines such as IL-1β and IL-6 may play a pivotal role." (PMID 28286408, 2017). "We next examined if BZA treatment could decrease IL-6-mediated stemness phenotype in cancer cells." (PMID 28978005, 2017).
cancer (continued). "Taken together, our findings show that IL-6 trans-signaling strongly accelerates autophagy in several cell types, including muscle, and may contribute to the pathogenesis of cachexia and survival of cancer patients." (PMID 28515477, 2017). "Thus, the elevated serum IL-6 level in cancer patients after surgery may promote the recurrence of patients with postoperative fever." (PMID 28977974, 2017). "Together, our findings suggest that IL-6 trans-signaling may be targeted in cancer cachexia." (PMID 28515477, 2017). "Moreover, we examined whether pimozide reversed the phenotypes of cancer stem-like cells induced by IL-6 treatment in HCC cells." (PMID 26061710, 2017). "However, -174G>C is the most famous SNP in IL-6 promoter region which is related to cancer." (PMID 28548958, 2017). "Thus, anti-thrombosis treatments, including heparin and anti-interleukin 6 antibody, in cancer patients could prolong survival by interfering with the crosstalk between tumors and platelets." (PMID 29228624, 2017). "The archetypal pro-inflammatory cytokine IL-6, which dictates the transition from acute to chronic inflammation, might illustrate how inflammation could have both a beneficial and a harmful role in aging and cancer." (PMID 28529938, 2017). "Moreover, IL-6 could have a crucial role in the activation of androgen receptor (AR) in cancer cells." (PMID 28389628, 2017). "This raised the question of whether effective therapeutic approaches in children with NBL could be based on the targeting of inflammation-associated biologic pathways in the TME, for example using an anti-IL-6 monoclonal antibody (mAb) to target the IL-6 pathway as evaluated in adult cancers." (PMID 29207662, 2017). "Nevertheless, it was suggested that one specific cytokine pattern may have a prognostic effect, since high interleukin 6 or interleukin 10 serum concentrations are associated with negative prognoses in independent types of cancer." (PMID 26905729, 2016). "However, in cancer cells, IL-6 induces DNMT1 to inhibit miR-370 expression." (PMID 27499248, 2016). "Future investigations on the roles of the IL-6 classical and trans-signaling pathways in both immune and non-immune cells in skeletal muscle tissue will provide new basis for therapeutic approaches to reverse atrophy and degeneration of skeletal muscles in cancer and inflammatory diseases." (PMID 27330885, 2016). "Moreover, several GT genes were shown to be regulated at the transcriptional level by pro-inflammatory cytokines such as tumor necrosis factor (TNF) or interleukin 6 (IL-6), leading to the expression of sialylated structures such as sLex also observed in cancers." (PMID 27916834, 2016). "Moreover, IL-6 has been suggested to be involved in the pathology of cancer." (PMID 27068103, 2016). "IL-6 plays an important role in immune responses and repair processes through classic-signaling, and may be involved in the pathogenesis of inflammatory diseases and cancers through trans-signaling." (PMID 26840088, 2016). "Therefore, we suggested that IL-6- or VEGF-induced signaling change in cancer cells might have less influence on their receptors." (PMID 26950598, 2016). "Furthermore, IL-6 expression renders tumor cells resistant to anti-cancer therapies." (PMID 27694691, 2016). "Although a large number of growth factors and cytokines can stimulate STAT3 activity, which could have synergistic effects on prolonging STAT3 activation, many growth factors, cytokines and other factors that induce STAT3 activity in inflammation and cancer require the IL-6 signaling pathway." (PMID 26501341, 2015). "Undoubtedly, therefore, involvement of certain interleukins including IL-6, IL-4, IL-17A and IL-32β in certain EMT pathways signifies their specific contribution to metastatic processes, thereby warranting further work into the development of diagnostic and immunotherapeutic tools in cancer." (PMID 25590298, 2015).